HDHD3 (haloacid dehalogenase like hydrolase domain containing 3)
Synonyms: C9orf158; MGC12904; 2810435D12Rik
Tractability: Small molecule: it has a high-quality binding pocket. PROTAC: ubiquitination databases record sites on it; its protein half-life has been measured.
Gene: Protein-coding gene on chromosome 9 (113,373,417 to 113,377,473, reverse strand). Ensembl gene ENSG00000119431.
Subcellular location (Human Protein Atlas): Nucleoli; Vesicles
Gene Ontology:
Molecular function: protein binding
Cellular component: mitochondrion; nucleolus; nucleus
Genetic constraint (gnomAD): Loss-of-function variants: 11 observed, 13.03 expected, observed/expected ratio (o/e) 0.84, 90% interval 0.53 to 1.39. The upper end of that interval is the gene's LOEUF score, 1.39, which puts it in group 5 of 6, group 1 being the genes least tolerant of losing a copy. Missense variants: 194 observed, 202.52 expected, observed/expected ratio (o/e) 0.96, 90% interval 0.85 to 1.08. Synonymous variants: 92 observed, 89.4 expected, observed/expected ratio (o/e) 1.03, 90% interval 0.87 to 1.22.
Homologues: Orthologues: chimpanzee HDHD3 (99% identical), macaque HDHD3 (96% identical), rabbit HDHD3 (82% identical), dog HDHD3 (78% identical), guinea pig HDHD3 (78% identical), mouse Hdhd3 (76% identical), pig HDHD3 (76% identical), rat Hdhd3 (76% identical), tropical clawed frog HDHD3 (49% identical), zebrafish hdhd3 (39% identical), Drosophila melanogaster CG15912 (32% identical), Drosophila melanogaster Reg-2 (28% identical), and 1 more. Paralogues in human: NANP (20% identical).
Diseases named in the same sentence as HDHD3 in open-access papers:
HDHD3 is named in the same sentence as 3 diseases in open-access papers, as found by Europe PMC text mining. Sharing a sentence is not in itself a finding about the gene and the disease.
HDHD3 shares sentences with these, for which no sentence is quoted: diabetic kidney disease (1 paper); Hepatic steatosis (1); Nephropathy (1).